FTX (FTX transcript, XIST regulator)
Synonyms: LINC00182; FLJ33139; MIR374AHG; NCRNA00182
Gene: Long non-coding RNA gene on chromosome X (73,940,435 to 74,293,574, reverse strand). Ensembl gene ENSG00000230590.
Gene Ontology:
Biological process: miRNA-mediated post-transcriptional gene silencing; positive regulation of gene expression; SRP-dependent cotranslational protein targeting to membrane, signal sequence recognition
Cellular component: signal recognition particle, endoplasmic reticulum targeting
Diseases named in the same sentence as FTX in open-access papers:
FTX is named in the same sentence as 64 diseases in open-access papers, as found by Europe PMC text mining. Sharing a sentence is not in itself a finding about the gene and the disease. The quoted sentences say what the papers report.
hepatocellular carcinoma (17 papers, 2019 to 2025). A malignant tumor that arises from hepatocytes. "Lnc-FTX inhibited hepatocellular carcinoma growth and metastasis by competitively binding to miR-374a and mini-chromosome maintenance complex component 2 (MCM2), which inhibited Wnt/β-catenin signaling and DNA replication." (PMID 39256355, 2024). "In this regard, RIG-I has been regarded as a functional downstream mediator of the lncRNA five prime to Xist (FTX)/miR-545 axis in hepatocellular carcinoma (HCC) cells." (PMID 36439216, 2022). "It has been reported that FTX was commonly upregulated in several human cancers and closely participate in tumor behaviors to promote cancer progression including hepatocellular carcinoma, lung adenocarcinoma, and gastric cancer." (PMID 34720057, 2021). "Abnormal expression of lncRNA FTX has been observed in liver cell carcinoma, renal cell carcinoma, colorectal cancer, and other cancers." (PMID 33736615, 2021). "Consistently, enhanced expression of FTX contributed to cell proliferation of hepatocellular carcinoma cells by interacting with miR-545 and regulating RIG-I expression." (PMID 33817286, 2020). "The abundance of FTX is thought to influence cell viability, invasion, and aerobic glycolysis of hepatocellular carcinoma cells by regulating the PPARγ pathway." (PMID 33817286, 2020). "FTX has been supported as a ceRNA in several tumors, such as hepatocellular carcinoma, osteosarcoma and colorectal cancer." (PMID 32226311, 2020). "FTX was reported to inhibit hepatocellular carcinoma proliferation and metastasis by binding MCM2 and miR-374a." (PMID 30764831, 2019). "Studies have found that lncRNA FTX (five prime to Xist) was abnormally expressed in various cancers, such as hepatocellular carcinoma, renal cell carcinoma and colorectal cancer, but the regulation of lncRNA FTX in PC remains unclear." (PMID 33736615, 2021). "However, FTX has also been shown to serve as a tumor suppressor by reducing cell progression in hepatocellular carcinoma by targeting miR-374a." (PMID 33817286, 2020). "A study of hepatocellular carcinoma (HCC) showed that long noncoding RNA FTX (lnc-FTX) binds to MCM2 and results in the arrest of DNA replication, causing lower proliferation of HCC cells." (PMID 40005158, 2025). "However, the expression of lnc-FTX was significantly decreased in female hepatocellular carcinoma." (PMID 39256355, 2024). "FTX, another lncRNA involved in X inactivation, has been identified as a putative tumor suppressor in hepatocellular carcinoma (HCC)." (PMID 32295632, 2020). "LncRNA FTX has been shown to regulate cancer cell proliferation, motility, and aberrant metabolism in many cancers, including colorectal cancer (CRC), hepatocellular carcinoma (HCC), and renal cell carcinoma (RCC)." (PMID 37993428, 2023). "Another studies discovered that FTX could inhibit the proliferation and metastasis of lung cancer cells by activating FOXA2 or could suppress the proliferation of hepatocellular carcinoma cells by impeding DNA replication." (PMID 37106382, 2023). "miR-545 derived from lncRNA FTX directly targets RIG-I and abrogates its expression, thus prompting the advancement of hepatocellular carcinoma (HCC)." (PMID 37662910, 2023).
colorectal cancer (14 papers, 2017 to 2025). A primary or metastatic malignant neoplasm that affects the colon or rectum. "Five prime to xist (FTX) is a lncRNA that is encoded by the FTX gene and was reported as an oncogene to participate in cancer progression in colorectal cancer, osteosarcoma, and renal cell carcinoma." (PMID 34720057, 2021). "In addition, significantly higher expression of the escape long noncoding FTX gene has been reported in colorectal cancer, although the downregulation of FTX is also associated with primary breast tumors." (PMID 28686623, 2017). "Subsequently, numerous studies have demonstrated up-regulation of Lnc-FTX in diverse cancers, including gastric cancer 19, colorectal cancer 20, and other digestive cancers." (PMID 40084261, 2025). "The long non-coding RNA (lncRNA) FTX is significantly upregulated in the cancer tissues, serum, and colorectal cancer cell lines of patients with colorectal cancer." (PMID 41311582, 2025). "FTX has been reported to act as a tumor promoter in various types of cancer, including osteosarcoma, colorectal cancer, gliomas, lung adenocarcinoma, and gastric cancer, where it was found to be closely associated with a poor prognosis." (PMID 37218885, 2023). "FTX was proven to promote the malignant progression of colorectal cancer by targeting the miR-214-5p-JAG1 axis or directly binding to miR-192-5p." (PMID 37106382, 2023). "It has been demonstrated that FTX is distributed in the colorectal cancer (CRC) cell nucleus and cytoplasm and drives the malignant progression of CRC by regulating miR-214-5p/JAG1 axis." (PMID 37993428, 2023). "FTX also interacts with different miRNAs in different types of human cancer, such as miR-590-5p in colorectal cancer, miR-214-5p in osteosarcoma, and miR-335-5p in lung adenocarcinoma." (PMID 34720057, 2021). "For instance, FTX indicated poor prognosis of colorectal cancer patients, and overexpression of FTX expedited the malignancy of colorectal cancer by accelerating cell growth." (PMID 33817286, 2020). "Evidence indicated that FTX could promote the migration, proliferation, and invasion for several caners, including colorectal cancer, gastric cancer, and lung cancer." (PMID 35444943, 2022). "In addition, FTX was reported as a ceRNA and played oncogenic role in colorectal cancer and gliomas." (PMID 32226311, 2020). "The long non-coding RNA (lncRNA) FTX elevates the levels of YAP1 by acting as a sponge for miR-215-3p, which in turn enhances aerobic glycolysis, cellular proliferation, migration, and invasion in colorectal cancer cells." (PMID 41311582, 2025). "The up-regulation of FTX could serve as an important prognostic factor in CRC patients by promoting growth, migration, invasion and increasing colony formation in colorectal cancer cells." (PMID 28658310, 2017).
glioma (8 papers, 2018 to 2023). A benign or malignant brain and spinal cord tumor that arises from glial cells (astrocytes, oligodendrocytes, ependymal cells). "FTX is also endowed with an oncogenic role in glioma, where it is upregulated and promotes cell proliferation and invasion by binding miR-342-3p, resulting in an increased expression of its target AEG-1." (PMID 35054794, 2022). "Conversely, a significant association between high FTX expression and a shorter OS in patients with CRC, GC, HCC, OSC, and glioma, or a shorter DFS in patients with HCC was observed." (PMID 33398336, 2021). "FTX may be a potential oncogene, and its high expression be associated with a poor prognosis in patients with CRC, HCC, OSC, and glioma." (PMID 33398336, 2021). "Taken together, these results suggested that FTX may be a candidate oncogene, and the overexpression of FTX was associated with a poor prognosis in common solid malignant tumors, such as CRC, HCC, OSC, and glioma." (PMID 33398336, 2021). "LncRNA FTX was observed to be up-regulated in glioma and boost cell proliferation and invasion." (PMID 32226311, 2020). "Interestingly, FTX promotes glioma proliferation and invasion through the binding of specific miRNA, and as the editing can alter the miRNA binding ability on RNA targets, we searched for the miRNA–lncRNA interactions." (PMID 33066171, 2020). "It makes FTX a very promising target for novel treatments of glioma." (PMID 30583549, 2018). "It makes lncRNA FTX a very promising target for novel treatment of glioma." (PMID 30583549, 2018). "In addition, it was reported that FTX was upregulated in gliomas cells and could inhibit the expression of miR-342-3p." (PMID 33736615, 2021). "The pooled results from the survival analysis revealed a significant correlation between high FTX expression and shorter OS in patients with HCC, CRC, GC, OSC, and glioma." (PMID 33398336, 2021). "Distinctively dysregulated lncRNAs in gliomas include LOC150622 and LINC00645 in glioblastoma, LOC100216479 in diffuse H3K27M glioma, FLJ41350 and FTX in medulloblastoma, TPTEP1 and LOC100144595 in astrocytoma, and LOC100216545, FAM66B, and LOC100499405 in oligodendroglioma." (PMID 37693314, 2023). "Similar considerations could also be applied for glioma and colon and gastric cancer where both XIST and its positive regulator FTX seem to have an oncogenic role." (PMID 35054794, 2022). "Further meta-analysis showed that high FTX expression could be an independent predictive marker for shorter OS in patients with CRC, HCC, OSC, and glioma." (PMID 33398336, 2021). "Further, FTX overexpression could be an independent predictive marker for shorter OS in patients with CRC, HCC, OSC, and glioma." (PMID 33398336, 2021).
gastric cancer (6 papers, 2020 to 2023). A primary or metastatic malignant neoplasm involving the stomach. "For example, lncRNAs FTX facilitated the progression of gastric cancer via sponging miR-144 to elevate ZFX." (PMID 33298078, 2020). "Increasing studies have shown that FTX is related to the clinicopathological features and prognosis of patients with cancer, including colorectal cancer (CRC), osteosarcoma (OSC), gastric cancer (GC), and renal cell carcinoma (RCC)." (PMID 33398336, 2021). "Additionally, in gastric cancer FTX exerts a similar functional role via the miR-144/ZFX and miR-215-3p/SIVA1 regulatory axis in promoting tumorigenesis; in addition, FTX was upregulated in tumor tissues in comparison to adjacent non-tumor tissues and correlated to poor prognosis." (PMID 35054794, 2022).
osteosarcoma (6 papers, 2020 to 2023). A usually aggressive malignant bone-forming mesenchymal neoplasm, predominantly affecting adolescents and young adults. "FTX is involved in medullary thyroid cancer, osteosarcoma, pancreatic cancer, and other diseases and plays an important role in the development of inflammation." (PMID 36874406, 2023). "Interestingly, RT-qPCR revealed that FTX was upregulated in osteosarcoma and was reduced in myocardial I/R injury patients' serum and H/R-stimulated H9c2 cells." (PMID 36874406, 2023).
acute myeloid leukemia (5 papers, 2020 to 2022). Acute myeloid leukemia (AML) is a group of neoplasms arising from precursor cells committed to the myeloid cell-line differentiation. "Moreover, FTX could regulate drug resistance of adriamycin against acute myeloid leukemia cells by competitively binding to miR-342 and altering ALG3 expression." (PMID 33817286, 2020). "The interaction between FTX and miR-342 was also validated in acute myeloid leukemia cells, resulting in the upregulation of another miRNA target, the ALG3 mannosyltransferase, thus contributing to drug resistance in acute myeloid leukemia." (PMID 35054794, 2022).
lung adenocarcinoma (5 papers, 2020 to 2025). A carcinoma that arises from the lung and is characterized by the presence of malignant glandular epithelial cells. "A study on lung adenocarcinoma demonstrated that Lnc-FTX is upregulated in tumor tissues and accelerates malignant characteristics of Lung adenocarcinoma by activating the miR-335-5p/NUCB2 pathway." (PMID 40084261, 2025).
lung carcinoma (5 papers, 2020 to 2024). "Since there are no reports of FTX in lung cancer, we first decided to examine the subcellular distribution of FTX in lung cancer cells." (PMID 32176463, 2020). "These collecting data demonstrate that FTX acts as a sponge of miR‐200a‐3p to activate FOXA2 expression in lung cancer cells." (PMID 32176463, 2020). "Enforced expression of FTX in lung cancer cells suppressed cancer growth and metastasis in vitro and in vivo." (PMID 32176463, 2020). "Then, we used a xenograft mouse model to clarify that FTX had growth‐inhibiting effect on lung cancer cells." (PMID 32176463, 2020). "To further explore the impact of FTX during lung cancer development, we overexpressed FTX (FTX‐OE) in A549 and H1299 cells using lentivirus." (PMID 32176463, 2020). "Our results provide new insights and directions for exploring the function of FTX in lung cancer progression." (PMID 32176463, 2020). "Ectopic expression of FTX inhibits proliferation and metastasis of lung cancer cells in vitro and in vivo." (PMID 32176463, 2020). "We reveal a novel role of FTX in cancer cell growth and metastasis, providing a potential biomarker and therapeutic target in lung cancer diagnosis and treatment." (PMID 32176463, 2020). "To explore potential molecular mechanism of FTX in lung cancer, we predicted competing endogenous (ceRNA) regulatory networks of FTX using online bioinformatics programmes including Targetscan, DIANA, starBase and RNAhybrid." (PMID 32176463, 2020). "The result indicated that FTX expression was decreased in lung cancer cell lines compared to IMR90 cells." (PMID 32176463, 2020). "To explore the function of FTX in lung cancer metastasis in an in vivo mouse model, we injected vector control or FTX‐OE A549 bioluminescent cells into severe combined immunodeficiency (SCID) mice through tail vein." (PMID 32176463, 2020). "Moreover, we found that FTX overexpression in lung cancer cells promoted cell apoptosis and induced cell cycle arrest at G0/G1 phase." (PMID 32176463, 2020). "The result of RNA pull‐down assay suggested that FTX interacted with miR‐200a‐3p in lung cancer cells, and Luciferase Reporter Gene Assay indicated that miR‐200a‐3p could both target FTX and FOXA2 genes." (PMID 32176463, 2020). "Firstly, we investigated whether forced expression of FTX had an effect on migratory and invasive capabilities of lung cancer cells." (PMID 32176463, 2020). "We found that FTX mRNA levels were down‐regulated in lung cancer clinical tissue samples." (PMID 32176463, 2020). "We next explored the impact of FTX overexpression on lung cancer cell growth." (PMID 32176463, 2020). "In summary, our study demonstrates that FTX may function as a tumour suppressor gene and regulate lung cancer development through acting as a sponge of miR‐200a‐3p to promote FOXA2 expression." (PMID 32176463, 2020). "Furthermore, we analysed mRNA expression level of FTX in four independent lung cancer cell lines as well as in IMR90 lung fibroblast cells." (PMID 32176463, 2020). "These in vivo data suggest FTX inhibits lung cancer proliferation." (PMID 32176463, 2020). "Furthermore, we find that FTX overexpression activates the expression of transcription factor FOXA2, an important regulator in lung cancer progression, and we reveal a novel FTX/miR‐200a‐3p/FOXA2 competing endogenous RNA regulatory axis in lung cancer cells." (PMID 32176463, 2020). "FTX overexpression inhibited lung cancer cell proliferation and metastasis via interacting with miR‐200a‐3p to promote FOXA2 expression, suggesting that FTX may act as a tumour suppressor in lung cancer progression." (PMID 32176463, 2020). "Furthermore, we revealed a novel FTX/miR‐200a‐3p/FOXA2 signalling axis in lung cancer progression." (PMID 32176463, 2020). "Moreover, FTX overexpression also inhibited miR‐200a‐3p expression in lung cancer cells." (PMID 32176463, 2020).
lung carcinoma (continued). "For example, FTX within exosomes derived from CAFs suppresses ferroptosis in oral squamous cell carcinoma, while ROR1-AS1 curbs this form of cell death in lung cancer cells." (PMID 39717771, 2024). "This is exemplified in various cancers: TUG1 in liver cancer; MEG3 and HOTAIRM1 in lung cancer; LINC00355 in bladder cancer; TUC338 in laryngeal squamous cell carcinoma; FTX in oral squamous cell carcinoma; and NNT-AS1 in pancreatic cancer." (PMID 39717771, 2024). "FTX overexpression activated FOXA2 expression, while transfection of miR‐200a‐3p mimics inhibited FOXA2 expression in lung cancer cells." (PMID 32176463, 2020). "Furthermore, we demonstrated that FOXA2 was a downstream target of FTX, while rescue experiments indicated that silencing of FOXA2 attenuated the effect of FTX on lung cancer growth and metastasis." (PMID 32176463, 2020). "To test whether FOXA2 is critical for FTX‐mediated inhibition of lung cancer cell growth and metastasis, we silenced FOXA2 expression in FTX‐OE A549 cells to do rescue experiments." (PMID 32176463, 2020). "However, the functional role of FTX in lung cancer progression was not clear." (PMID 32176463, 2020).
renal cell carcinoma (5 papers, 2021 to 2025). "The long non-coding RNA (lncRNA) FTX displays activities in promoting renal cell carcinoma proliferation; its upregulation may re-initiate podocyte proliferation, which will damage podocytes." (PMID 40149392, 2025).
pancreatic cancer (4 papers, 2021 to 2024). "Combining in vivo and in vitro results, we confirmed that silencing of FTX suppressed pancreatic cancer cell proliferation and invasion by upregulating miR-513b-5p." (PMID 33736615, 2021). "Therefore, silencing of FTX suppressed pancreatic cancer cell proliferation and invasion though upregulating miR-513b-5p." (PMID 33736615, 2021). "This phenomenon is exemplified in various cancers: WEE2-AS1 and SNHG3 in colorectal cancer; NEAT1 in endometrial cancer; LINC00355 in bladder cancer; SNHG3 in breast cancer; TUC338 in laryngeal squamous cell carcinoma; FTX in oral squamous cell carcinoma; and NNT-AS1 in pancreatic cancer." (PMID 39717771, 2024). "However, the effect of FTX on the development of pancreatic cancer (PC) has not been elucidated." (PMID 33736615, 2021).
colon cancer (3 papers, 2020 to 2021). "Recently, a screen for co-expressed miRNA-host gene pairs in colon cancer identified FTX as an oncogenic host gene harboring several intronic miRNAs." (PMID 34572454, 2021). "Thus, FTX overexpression along with its intronic miRNAs miR-374b and miR-545 promote colon cancer via two different but synergistic oncogenic pathways." (PMID 34572454, 2021).
ovarian carcinoma (3 papers, 2021 to 2024). A malignant neoplasm originating from the surface ovarian epithelium. "To determine whether XIST, JPX, and FTX downregulation could be caused by chromosomal deletions, we also examined Copy Number Variation (CNV) across ovarian cancer grades." (PMID 39546568, 2024).
Stroke (3 papers, 2023 to 2025). Sudden impairment of blood flow to a part of the brain due to occlusion or rupture of an artery to the brain. "Recent studies have also shown that FTX participates in the apoptosis of neurons or cardiomyocytes and regulates the angiogenesis in stroke or hypoxia/reoxygenation-induced cardiomyocyte injury, suggesting that FTX may be involved in the apoptosis of adult cells and the repair of tissue injury." (PMID 37106382, 2023). "For example, the lncRNA FTX acts as a sponge for miR-342-3p to regulate SPI1 expression levels, enhancing angiogenesis in stroke." (PMID 39847586, 2025).
breast tumor (2 papers, 2014 to 2017). "Previously identified chromatin-associated lncRNAs (CARs) were predominantly downregulated in breast tumor samples, including CARs located in the protein-coding genes for CALD1, FTX, and HNRNPH1." (PMID 25264628, 2014).